CHD8 (chromodomain helicase DNA binding protein 8)
Diseases named in the same sentence as CHD8 in open-access papers (continued):
Sharing a sentence is not in itself a finding about the gene and the disease.
autism spectrum disorder (62 papers, 2012 to 2025). A spectrum of developmental disorders that includes autism, and Asperger syndrome. "CHD8 was originally identified as one of the most frequently mutated genes in autism spectrum disorders (ASDs)." (PMID 41226840, 2025). "Chromodomain helicase DNA-binding protein 8 (CHD8), a frequently mutated gene in autism spectrum disorder (ASD), is an ATP-dependent chromatin remodeler with emerging roles in hematopoiesis." (PMID 41226840, 2025). "Yet another study into Chd8, a DNA binding protein implicated in chromatin remodelling, autism spectrum disorder and CHD8-related overgrowth disorder, revealed how gene dosage drives distinct outcomes for brain growth." (PMID 41023182, 2025). "In the current study, we analyzed the influence of CHD8 gene polymorphisms on the occurrence and clinical phenotype of autism spectrum disorders." (PMID 39685474, 2024). "Approximately 30% of CHARGE-associated Chd7 mutations lie within functional domains including the ATPase domain and the percentage of Chd8 point mutations within the ATPase domain associated with autism spectrum disorders is 8%." (PMID 38512854, 2024). "The aim of this study was to perform an analysis of the family-based association of CHD8 gene polymorphisms with the occurrence and clinical phenotype of autism spectrum disorder (ASD)." (PMID 39685474, 2024). "CHD8 encodes chromodomain helicase DNA-binding protein 8 and its mutation is a highly penetrant risk factor for autism spectrum disorder (ASD)." (PMID 37268684, 2023). "Chromodomain helicase DNA-binding protein 8 (CHD8) is mutated in individuals with autism spectrum disorder, and heterozygous mice with CHD8 mutations are known to exhibit significant ASD properties." (PMID 37338366, 2023). "Disruptive mutations in the chromodomain helicase DNA-binding protein 8 gene (CHD8) have been recurrently associated with autism spectrum disorders (ASDs)." (PMID 36537238, 2022). "The chromodomain helicase DNA-binding protein CHD8 is the most frequently mutated gene in autism spectrum disorder." (PMID 36575212, 2022). "Mutations identified in individuals with autism spectrum disorder (ASD) are distributed throughout the CHD8 locus, with some predicted mutations resulting in the loss of both CHD8 isoforms, while others affect only CHD8L." (PMID 33933000, 2021). "Autism spectrum disorders (ASD) are associated with mutations of chromodomain-helicase DNA-binding protein 8 (Chd8) and tuberous sclerosis complex 2 (Tsc2)." (PMID 34497307, 2021). "Chromodomain helicase domain 8 (CHD8) is one of the most frequently mutated and most penetrant genes in the autism spectrum disorder (ASD)." (PMID 33806835, 2021). "While CHD8 is associated with autism spectrum disorder, its function for neural crest development has never been reported." (PMID 33554859, 2021). "Heterozygous mutation of chromodomain helicase DNA binding protein 8 (CHD8) is strongly associated with autism spectrum disorder (ASD) and results in dysregulated expression of neurodevelopmental and synaptic genes during brain development." (PMID 33837267, 2021). "Chromodomain helicase DNA-binding protein 8 (Chd8) is a high-confidence risk gene for autism spectrum disorder (ASD)." (PMID 33023670, 2020). "CHD8 encodes a chromatin-remodeling factor and is one of the most recurrently mutated genes in individuals with autism spectrum disorder (ASD)." (PMID 33228730, 2020). "CHD8 is a high-risk factor for autism spectrum disorder and patients with CHD8 mutations characteristically present macrocephaly and distinctive facial features." (PMID 32299352, 2020). "Truncating CHD8 mutations are amongst the highest confidence risk factors for autism spectrum disorder (ASD) identified to date." (PMID 29668850, 2018). "Mutations in CHD8, chromodomain helicase DNA-binding protein 8, are among the most replicated and common findings in genetic studies of autism spectrum disorder (ASD)." (PMID 30574290, 2018).
autism spectrum disorder (continued). "Chromodomain helicase DNA binding protein 8 (CHD8) encodes a chromatin remodeling factor with among the highest de novo loss-of-function mutation rates in patients with autism spectrum disorder (ASD)." (PMID 30692911, 2018). "Disruptive mutation in the CHD8 gene is one of the top genetic risk factors in autism spectrum disorders (ASDs)." (PMID 26491539, 2015). "CHD8 mutations cause autism spectrum disorder, cognitive deficits, and macrocephaly." (PMID 40799750, 2025). "However, a case of autism spectrum disorder with a paternally inherited CHD8 variant (p.Arg1797Gln) has been reported." (PMID 41407309, 2025). "Some of these may include CHD7 causing CHARGE syndrome (MIM #214800), CHD4 as causative of Sifrim–Hitz–Weiss syndrome (MIM #603277), or CHD8 causing autism spectrum disorder (MIM #610528)." (PMID 37761804, 2023). "Furthermore, we detected significant enrichment of the chromatin remodeler CHD8, which genome-wide association studies have shown to be strongly associated with the risk of autism spectrum disorder in humans and in mouse models." (PMID 35073843, 2022). "Targeted DamID in embryonic mouse cortex characterizing CHD8 binding sites, a chromatin remodeler with de novo mutation associated with sporadic autism spectrum disorder, indicated that binding of CHD8 at distal enhancers regulates neurodevelopment-associated genes, e.g., ANK3." (PMID 34299232, 2021). "CHD proteins play an important role in neurodevelopment, as pathogenic variants in CHD1, CHD2, CHD4, CHD7 and CHD8 have been associated with a range of neurological phenotypes, including autism spectrum disorder (ASD), intellectual disability (ID) and epilepsy." (PMID 29962935, 2018). "Among the many genes in region are ZNF219, which encodes a transcriptional partner of Sox9 essential for chondrogenesis in mice, and CHD8, mutations in which are associated with autism spectrum disorder in conjunction with macrocephaly and distinct facial features including a broad nose." (PMID 27560520, 2016). "The condition was first reported in 2011 among a group of individuals with sporadic autism spectrum disorder (ASD), and the characterization of CHD8 functions facilitated the establishment of an association between CHD8 variants and IDDAM." (PMID 40496977, 2025). "Kis is the homolog of CHD7 and CHD8, both of which are implicated in neurodevelopmental disorders including CHARGE Syndrome and autism spectrum disorders, respectively." (PMID 39125997, 2024). "Both proteins are important for proper neural development as heterozygous mutations in Chd7 and Chd8 are causative for CHARGE syndrome and correlated with autism spectrum disorders, respectively." (PMID 38512854, 2024). "Hundreds of genes have been associated with autism spectrum disorder (ASD), including loss-of-function mutations in chromodomain helicase DNA binding protein 8 (Chd8)." (PMID 35365720, 2022). "Disease-causing variants in CHD7 and CHD8 cause CHARGE syndrome and a syndromic form of autism spectrum disorder, respectively." (PMID 33944996, 2021). "The chromatin remodeler CHD8, which belongs to the ATP-dependent chromatin remodelers CHD family, is one of the most high-risk mutated genes in autism spectrum disorders." (PMID 34686651, 2021). "We further validate the increased transcriptional heterogeneity in CHD8+/− cells, a model for autism spectrum disorder." (PMID 33663567, 2021). "Chromodomain helicase DNA-binding protein 8 (CHD8) was identified as a leading autism spectrum disorder (ASD) candidate gene by whole-exome sequencing and subsequent targeted-sequencing studies." (PMID 25989142, 2015).
autism spectrum disorder (continued). "Moreover, the research found that in Chd8+/− mice model of autism spectrum disorder (ASD), increased expression of neutral amino acid transporters Slc6a19, Slc7a8, and Slc7a15 resulted in increased serum glutamine and tryptophan levels." (PMID 36620044, 2022). "This was also the case for isogenic CHD8+/+ and CHD8+/− cells, a cellular model for autism spectrum disorder (ASD), consistent with our hypothesis that damaged neural cells have an increased cellular variability." (PMID 33663567, 2021). "CHD8 (chromodomain helicase DNA-binding protein 8), which codes for a member of the CHD family of ATP-dependent chromatin-remodeling factors, is one of the most commonly mutated genes in autism spectrum disorders (ASD) identified in exome-sequencing studies." (PMID 28321286, 2017). "Although implicated as a risk factor in autism spectrum disorder and a tumor suppressor in prostate and lung cancer, the mechanism of CHD8’s activity is still unclear and has never been studied in the context of hematopoietic malignancies." (PMID 26588464, 2015). "CHD8 (Chromodomain-Helicase-DNA-binding protein 8), a member of CHD family that is characterized by a SNF2-like ATPase domain and two chromatin organization modifier domains, is identified as one of the most high-risk mutated genes in autism spectrum disorders (ASD)." (PMID 34686651, 2021). "Furthermore, the high Fam124B expression in the developing mouse brain and in neuronal tissues at embryonic day E12.5 might indicate a role of FAM124B together with CHD8 in neurodevelopmental and autism spectrum disorders." (PMID 23285124, 2012). "CHD8 and BCL11A are also both expressed in the brain and play important roles in autism spectrum disorders." (PMID 40328966, 2025). "While the daugther showed typical features of AUTS18/CHD8 (intellectual disability, autism spectrum disorder and macrocephaly), her father only displayed macrocephaly without any known neurodevelopmental features." (PMID 37872275, 2024). "Chromatin unwinding DNA-binding protein 8(CHD8) inhibited the onset of autism spectrum disorder (ASD), and the upregulation of miR-221 activated the Wnt/β-catenin pathway by binding to CHD8, which facilitating the differentiation from SHEDs to neurons." (PMID 35480302, 2022). "We previously demonstrated that a part of human CHD7 interacts with a part of human CHD8, another chromodomain helicase DNA binding protein presumably being involved in the pathogenesis of neurodevelopmental (NDD) and autism spectrum disorders (ASD)." (PMID 23285124, 2012). "Autism spectrum disorders (ASD) are ~4-times more common in males than females, and CHD8 (a chromatin remodeler)-related ASD shows a strong male bias (~4:1), although the underlying mechanism remains unclear." (PMID 36385756, 2022).
Anxiety (28 papers, 2016 to 2026). Intense feelings of nervousness, tension, or panic often arise in response to interpersonal stresses. "Since approximately 30% of individuals with CHD8 mutations display increased anxiety, these data suggest that this phenotype is tightly linked to gut dysregulation." (PMID 37783686, 2023). "Gut epithelial cell-specific Chd8 haploinsufficiency was associated with increased anxiety-related behaviors together with a decrease in tuft cell numbers." (PMID 37783686, 2023). "ASD-like symptoms, including social behavioral problems, repetitive activities, and increased anxiety, are observed in heterozygous individuals with CHD8 mutations." (PMID 35726297, 2022). "Interestingly, levels of complement subunit 3 (C3), an antimicrobial factor that has been implicated in anxiety, were upregulated in the amygdala of Chd8+/ΔIEC mice." (PMID 37783686, 2023). "CHD8 haploinsufficiency in oligodendrocytes caused anxiety-like behavior." (PMID 34440307, 2021). "However, individuals with ASD often report increased anxiety, including patients with truncating mutations in CHD8." (PMID 33023670, 2020). "The patients with the CHD8 DN mutation, for example, show ID (2/2), macrocephaly (2/2), tall stature (2/2), high BMI (2/2), mild regression (2/2), sleep problems (1/2), GI disturbance (1/2), attention deficit (2/2) and anxiety (1/2)." (PMID 27824329, 2016). "Increased pup crawl/run frequencies predicted Chd8+/− strain effect sizes for anxiety-like behavior in the BOF test in males (F1, 15 = 6.167, p<.05), with increased crawl/run frequencies associated with decreased effect sizes." (PMID 40092436, 2025). "In PAH rats, anxiety- and depression-like behaviors were observed, and qPCR confirmed altered expression of CHD8, DDX42, and EIF3D consistent with in-silico findings." (PMID 41280439, 2025). "This suggests that pup crawl/run is an early indicator of Chd8-driven increased anxiety effect sizes in adult males." (PMID 40092436, 2025). "Machine learning analysis reveals that early life litter experiences are strong predictors of sex-dependent postweaning social, anxiety-like, and cognitive trait disruptions due to Chd8 haploinsufficiency." (PMID 40092436, 2025). "A previous study reported that mice with heterozygous Chd8 gene deletion exhibited similar physiological and behavioral changes, including macrocephaly, excessive anxiety, repetitive behaviors, and abnormal social behaviors." (PMID 41425200, 2025). "Our findings align with a previous study using B6 mice that found that varying the ratio of co-housed Chd8+/− mice for 4 weeks beginning at weaning impacted social and anxiety-like behaviors, brain activity, and the microbiome of Chd8+/− mice." (PMID 40092436, 2025). "Strikingly, specific deletion of Chd8 from gut epithelial cells mice was sufficient to recapitulate the anxiety-like behaviors of Chd8L+/− mice carrying systemic Chd8L haploinsufficiency." (PMID 37783686, 2023). "A crucial finding in this study contradicted our results: when Chd8+/∆SL male mice were treated with oxytocin intraperitoneally, they stayed longer in the light area, suggesting that oxytocin rescued anxiety-like behavior in male mice." (PMID 36865037, 2023). "In the open field test, Chd8+/ΔIEC mice exhibited fewer visits to the center and decreased distance moved in the center, suggesting anxiety-like phenotypes, while total distance moved was comparable with that of WT controls." (PMID 37783686, 2023). "In the elevated plus maze test, Chd8+/ΔIEC mice spent less time in the open arms of the maze and moved less distance in the open arms, further indicating anxiety-like behavioral phenotypes." (PMID 37783686, 2023). "We also performed open-field and light/dark box tests to detect the effects of recovery of B. uniformis on the anxiety-like behavior of the Chd8+/− mice." (PMID 35241668, 2022).
Anxiety (continued). "Male and female Chd8+/S62X mice also showed normal levels of anxiety-like behaviors in elevated plus-maze and light–dark tests and social interaction in the juvenile play test, compared with WT mice." (PMID 36385756, 2022). "Given that ASD is characterized by early symptomatic manifestations and Chd8+/N2373K mice (C-terminal truncation) showed autistic-like enhanced anxiety-like behaviors in pup and juvenile stages, we examined early behavioral deficits in Chd8+/S62X mice." (PMID 36385756, 2022). "Adult male and female Chd8+/S62X mice showed largely similar deficits in repetitive and anxiety-like behavioral domains." (PMID 36385756, 2022). "Chd8+/E31T mice displayed normal anxiety-like behavior, repetitive self-grooming, learning impairments, and social interaction." (PMID 34440307, 2021). "With the possible exception of anxiety, the behavioural phenotypes of Chd8+/− and hypomorphic mice were remarkably similar, including robust, reproducible hypo-activity." (PMID 33627187, 2021). "Chd8+/∆SL male mice manifested increasing anxiety-like behavior in a range of behavioral tests, which partially replicates findings in patients with ASD." (PMID 33933000, 2021). "Interestingly, Chd8 hypomorphs showed increased aversion towards the centre of the open field arena, suggesting that reduced Chd8 expression may predispose to anxiety." (PMID 33627187, 2021). "Our novel finding, however, is that Chd8+/∆SL female mice spent longer in the dark, a sign of anxiety." (PMID 33933000, 2021). "Chd8+/ΔL mice demonstrated increased anxiety, repetitive behavior, and altered social behavior, in addition to neurodevelopmental delay in the embryos." (PMID 34440307, 2021). "More importantly was finding that when Chd8+/∆SL male mice were treated by i.p. injection of OT, they stayed longer in the light compartment (like WT male mice), indicating that OT rescued anxiety-like behavior in male mice." (PMID 33933000, 2021). "Reducing CHD8 expression in upper layer cortical neurons at this time point induced social behavior deficits and anxiety in the adult offspring." (PMID 34440307, 2021). "In Olig1-Cre/Chd8L+/F mice, decrease of CHD8 in oligodendrocytes led to abnormal behavior in mice, as expressed in increased social interaction and anxiety-like behavior." (PMID 34440307, 2021). "It has previously been shown that Chd8 haplodeficient male mice manifest ASD-like behavioral characteristics such as anxiety and altered social behavior." (PMID 33933000, 2021). "In contrast, CHD8 heterozygous (het) mice are viable and show increased anxiety, abnormal sensorimotor arousal and gating (as tested by prepulse inhibition paradigms), altered social interaction in some parameters and increased brain weight." (PMID 28680792, 2017). "We find that Chd8 mutation induced at embryonic day 14.5 gives rise to ASD-like behavioral phenotypes, including abnormal social interaction and increased anxiety-like behavior, as well as to accelerated cell-cycle exit and differentiation in ventral progenitor cells." (PMID 42203765, 2026). "In contrast, a different patient-derived mutation, CHD8 S62X, resulted in repetitive and anxiety-related behaviors in juvenile males (but not in females) and in adults (both sexes)." (PMID 40160416, 2025). "The current study sought to compare functional, cellular and molecular characteristics of the gut of Chd8L+/− vs. wild type (WT) mice, and to assess the possibility of a link between changes in GI signatures and the anxiety-like behavior that arises as a consequence of Chd8 haploinsufficiency." (PMID 37783686, 2023). "Specifically, Chd8 knockout in gut epithelial cells (CHD8+/ΔIEC) caused anxiety-like behaviors, without impacting social behavior." (PMID 37783686, 2023).